MTOR (mechanistic target of rapamycin kinase)
Diseases named in the same sentence as MTOR in open-access papers (continued):
Sharing a sentence is not in itself a finding about the gene and the disease.
tumor (continued). "CGA inhibited EGFR/PI3K/mTOR, HIF, VEGF pathways and MAPK/ERK pathway that may suppress tumor cell growth." (PMID 36386222, 2022). "mTOR-mediated regulation of STAT3 and NF-κB activity promoted an immunosuppressive microglial phenotype, which hindered effector T-cell infiltration, proliferation, and immune reactivity, thereby contributing to tumor immune evasion and tumor aggression." (PMID 35600367, 2022). "Additionally, we noted that procaine inhibited c-Met and its downstream signaling events such as PI3K/Akt/mTOR and MEK/ERK activation in tumor tissues." (PMID 36291760, 2022). "Chloroquine could substantiate the anti-tumor effects of pterostilbene on PC through the inhibition of autophagy via downregulating RAGE/STAT3 and protein kinase B (AKT)/mammalian target of rapamycin (mTOR) signaling pathway." (PMID 36408249, 2022). "They reported significantly lower recurrences of cutaneous malignancy with mTOR inhibitor after the initial diagnosis of tumor as well as lower non-skin cancer." (PMID 36003907, 2022). "Phosphatase and tensin homolog (PTEN), a tumor suppressor critical in mTOR pathway signaling, can function to dephosphorylate PIP3 at this stage, essentially turning “off” the cell signaling cascade prior to activation of mTOR." (PMID 35326708, 2022). "The canonical pathway for miR-21-induced oncogenesis is through to be the direct repression of various well-known tumor suppressor genes, including PTEN and PDCD4, which activate cyclin-dependent kinases, c-MYC, and PI3K/AKT/mTOR pathways, which results in an increased invasion and metastasis." (PMID 35216281, 2022). "In addition, PI3K/AKT/mTOR lead to epithelial-mesenchymal transition (EMT) in chemotherapy resistance and metastasis in malignant tumor cells." (PMID 36539659, 2022). "In the mice sarcoma model, glucose deprivation could inhibit the mTOR activity and IFN-γ production of tumor-infiltrating lymphocytes (TILs)." (PMID 36200045, 2022). "The PI3K/AKT (protein kinase B) and the mammalian target of rapamycin (mTOR) signaling pathways (PI3Kγ/AKT/mTOR) were able to inhibit NF-κB activation and stimulate C/EBPβ activation, thereby promoting immune suppression during tumour growth." (PMID 35406451, 2022). "Oxaliplatin treatment in PT CRC cells inhibited their proliferation by decreasing phospho-Akt, followed by decreasing phospho-mTOR and other downstream molecules, such as phospho-p70S6K and phospho-S6RP, resulting in the induction of tumor-suppressive autophagy in ST CRC cells." (PMID 36359211, 2022). "Furthermore, FBXO9 exerts a tumor-promoting effect in HCC by downregulating FBXW7, thereby increasing the protein levels of FBXW7 oncogenic substrates, such as mTOR." (PMID 35847937, 2022). "The effect however could not be reproduced in TLR4 null macrophages, corroborating that tumor-derived redHMGB1, via TLR4-sensing pathway, initiated the mTOR/Bcl6 program in macrophages." (PMID 36542153, 2022). "Under acidic conditions in the tumor microenvironment, the bioinspired nanoparticles rapidly cleave and release miR497 and TP, which synergistically induce OC cell apoptosis by inhibiting the PI3K/AKT/mTOR signaling pathway." (PMID 35078498, 2022). "Data analysis also showed that the CCL2, which enhanced tumor migration ability via the PI3K/AKT/mTOR pathway, is originated from adipocytes, not the tumor cell." (PMID 34386431, 2021). "Given that PI3K/AKT/mTOR signaling was activated in RCC patients, rapalogues were FDA approved for use in the clinic, however, these agents showed tumor regression in a minority of patients with the development of resistance being a major limitation of therapy." (PMID 34002003, 2021). "We will further make deeper and more detailed studies about regulation mechanism of PRMT5 on ESCC in the future work, including the inhibition LKB1/AMPK/mTOR pathway and whether PRMT5-siRNA has anti-tumor growth." (PMID 34124017, 2021).
tumor (continued). "Supporting this finding is the demonstration that 4EBP1/2 knockout mice are conducive to tumor growth, whereas the mutant mice with 4EBP1 that is non-phosphorylatable by mTOR limits tumor progression." (PMID 35048066, 2021). "The inhibition of mTOR attenuated the EIF4G1‐induced development and progression of tumours." (PMID 33523588, 2021). "The immunological roles of mTOR signaling and its involvement in the tumor microenvironment will not be discussed in this review but have been reviewed in detail elsewhere." (PMID 34208071, 2021). "Interestingly recent studies in a murine GBM model utilizing an alternative mTOR inhibitor, RES529, which has been shown to cross the blood-brain barrier, in combination with bevacizumab had reduced tumor progression and increased overall survival." (PMID 34077449, 2021). "As a tumor suppressor, miR-7 also increases CDDP sensitivity via targeting mTOR in GC cells." (PMID 34805143, 2021). "The AKT/mTOR pathway is a well‐studied anticancer pathway, and the PI3K/AKT/m TOR pathway has been found to be overactivated in liver cancer, cell survival, proliferation, migration, apoptosis, tumor metastasis, angiogenesis, and transformation." (PMID 34255431, 2021). "EGFR-induced mTOR can stimulate the expression of IL6 through the classic pathway and reprogram IL-6 nonresponsive cells into IL-6 responder cells, to further affect the sensitivity of the tumor cells to IL-6." (PMID 33582655, 2021). "Next, using above NSCLC subcutaneously transplanted tumor tissues, we further verified whether patchouli alcohol has a regulatory effect on AMPK, MAPK, and Akt/mTOR pathways." (PMID 34764997, 2021). "Under hypoxic conditions, stabilization of hypoxia-inducible factor-1-alpha (HIF-1α) enhances overexpression of the PI3K–Akt–mTOR pathway and glucose transporters (e.g., GLUT-1) to reinforce glucose consumption and acidification of the tumor microenvironment (TME)." (PMID 34885023, 2021). "Moreover, protein array analysis of ccRCC patient samples showed increased levels of phosphorylated mTOR and AKT 1/2/3 kinases, which are related to tumor invasiveness and metastasis." (PMID 34657130, 2021). "Standard treatments such as everolimus (inhibitor of mammalian target of rapamycin [mTOR]) and sunitinib (inhibitor of receptor tyrosine kinases, including VEGFR) were supported by patient tumor profiling and drug studies in RT2 mice demonstrating their effectiveness." (PMID 34199469, 2021). "Next, Western blotting was performed to investigate whether ethyl ferulate could inhibit protein expression of mTOR and its downstream signaling targets in PDX tumor tissues." (PMID 35155187, 2021). "It is important to mention that negative effects of mTOR inhibitors on the anti-tumor response induced by vaccination were reported." (PMID 33802831, 2021). "Moreover, PTEN is well known as a tumor inhibitor and phosphatidylinositol 3-kinase (PI3K)–mammalian target of rapamycin (mTOR) signaling inhibitor." (PMID 34368119, 2021). "The prediction results of the three databases were consistent, indicating that hsa_circ_0028861 played critical roles in several tumor-related signaling pathways such as integrin, vascular endothelial growth factor (VEGF), PI3K/Akt, and mTOR signaling pathways." (PMID 34367259, 2021). "More importantly, LY294002, an inhibitor of the PI3K/AKT/mTOR pathway, markedly reversed BCAT1-mediated tumorigenicity, including the phosphorylation of AKT; increased cell viability, proliferation, invasion, and angiogenesis; and tumor growth." (PMID 34164393, 2021). "Finally, metabolic changes in the hypoxia-induced tumor microenvironment under EGFR and mTOR inhibition, leading to adverse effects, have suggested the exact opposite approach." (PMID 34073734, 2021). "The mTOR inhibitors, sirolimus, everolimus, and temsirolimus, were the most active single agents tested, potently induced tumor-suppressive autophagy, but not apoptosis." (PMID 34331013, 2021).
tumor (continued). "Tumor growth rate was slightly less in individuals taking an mTOR inhibitor (−0.8 mm/yr, IQR: −2.3 to 2.2) than those without (1.6 mm/yr; IQR: −0.99 to 5.01) but the difference was not statistically significant (p > 0.05)." (PMID 33897589, 2021). "Additionally, we performed intracellular staining to measure phosphorylation levels of mTOR substrates, S6 kinase and 4E-BP1, among the samples extracted from the tumours to test for alteration in mTOR kinase activity." (PMID 33318657, 2021). "Therefore, balance between the anti-tumor activity and dose-tolerability has to be seriously considered in clinical trials with these dual PI3K/mTOR inhibitors." (PMID 33670113, 2021). "Several signaling pathways in tumor cells, including Akt, mTOR, STAT3, and Notch, may be responsible for the altered tumor environment exposed to tumor therapies." (PMID 33732706, 2021). "Notably, the contributions of miR-19, miR-21 and miR-221 to tumor growth are all related to their down-regulation of tumor suppressor PTEN, suggesting the role of PTEN and its downstream PI3K/Akt/mTOR signaling pathway in VS cancerigenic process." (PMID 34646772, 2021). "Interestingly, here we find that CE treatment activates AKT/MTOR/S6K in MCF-7 cells, and avasimibe suppresses tumor cell growth likely by inhibiting this signaling pathway." (PMID 34201030, 2021). "As expression level of p-AKT, p-mTOR or PI3K pathway scoring were not derived from pure tumor mass, but also included those of the infiltrating immune population and other stromal cells." (PMID 33874915, 2021). "We hypothesize that combined inhibition of transcription (by BET-protein inhibition) and translation (by mTOR inhibition) will synergistically blockade global protein synthesis and proliferation in MYC-driven NB tumor cells." (PMID 34565342, 2021). "The relationship between p-mTOR expression and patients’ sex, age or tumor grade was not significant (P = 0.056, P = 0.244, P = 0.397, respectively)." (PMID 34458019, 2021). "Thus, tumor-derived factors induced by miRNAs support the tumor growth and progression by regulating the activity of MDSCs via targeting PTEN, which activates the Akt/mTOR signaling axis." (PMID 35250965, 2021). "Thus, LQ inhibits tumor growth, induces cell apoptosis and autophagy and inactivates the PI3K/AKT/mTOR pathway in vivo." (PMID 34488535, 2021). "Tumor growth rate was slightly less in individuals taking an mTOR inhibitor (−0.8 mm/yr, IQR: −2.3 to 2.2) than those without (1.6 mm/yr; IQR: −0.99 to 5.01, p > 0.05)." (PMID 33897589, 2021). "The AKT/mTOR, NF-κB and ERK/MAPK signaling pathways are the main regulatory pathways of tumor EMT." (PMID 33591943, 2021). "This tumor suppressor acts as a competitive inhibitor of ATP in PI3K and mTOR." (PMID 34452203, 2021). "Application of GSEA showed that within each of PCS1, PCS2 and PCS3, HER2+ tumors were enriched for, e.g., MYC targets, and mTOR signaling in comparison to HER2− tumors, providing further evidence that HER2 status and BCCS provide independent information on tumor biology." (PMID 34642313, 2021). "The tumor suppressor PTEN is a negative regulator of the PI3K/Akt/mTOR signaling by converting PIP3 to PIP2 and preventing phosphorylation of Akt, further inhibiting the phosphorylation of mTOR." (PMID 33628319, 2021). "Further, the suppression of TU212 cell proliferation and consequent changes in the tumor volume and weight of nude mice after fisetin treatment were connected to decreased Ki67 levels and the inactivation of ERK1/2- and PI3K/AKT-regulated mTOR." (PMID 34950252, 2021). "Additionally, activation of the HGF-MET pathway by overexpression and up regulation has been described as the escape resistance mechanism of tumor cells against inhibition of the EGFR, RAS-RAF-MEK, and Akt–mTOR (mammalian target of rapamycin) pathways." (PMID 33918490, 2021).
tumor (continued). "However, GBM-N019-targeted mTOR/CDK6/STAT3 signature, supported by a wealth of literature, contributes to tumor progressions, stemness, distant metastasis, and regulation of immune checkpoint blockade therapy outcome." (PMID 34572040, 2021). "In another study, circ_100338 is reported to be up-regulated in HCC tissues, which is related to the poor prognosis of HCC patients; mechanistically, circ_100338 plays a tumor-promoting role via regulating the miR-141-3p/RHEB axis and controlling mTOR signal pathway." (PMID 34002672, 2021). "Could signaling pathways such as mTOR and AMPK, critical nutrient sensors, and metabolic regulators, also be involved in the anti-tumor immune response, downstream of the metabolic shift in GLUT1ΔmΦ macrophages?" (PMID 34198548, 2021). "Furthermore, knockdown of p62 significantly reduced the phosphorylation of mTORC1 (p-mTOR) in HCC cells and inhibited the viability of HCC cells in vitro and tumor growth in a xenograft mouse model." (PMID 33854041, 2021). "The direct anti-tumor effects of metformin appear to be modulated through activation of the adenosine monophosphate-activated protein kinase (AMPK) and inhibition of the mammalian target of rapamycin (mTOR) signaling pathway, which leads to inhibition of cell growth and proliferation." (PMID 34815475, 2021). "Finally, tumor types vary in terms of the duration and depth of responses to agents targeting the PI3K/Akt/mTOR pathway according to the degree of oncogenic addiction." (PMID 33723724, 2021). "In murine kidney TsC2+/- tumors, metformin was able to reduce mTOR signaling only in normal tissues but not in tumor cells." (PMID 33821877, 2021). "Interestingly, PD-1 blockade reverses glucose restriction in TILs (tumor killer cells), enhancing CD8+ T cells glucose influx and glycolysis via mTOR signaling, which allows IFN-γ production, improving their effector anti-tumor function." (PMID 33546704, 2021). "In addition, 15 μM and 30 μM curcumin treatments inhibited tumor p-AKT and p-mTOR expressions and increased cytoc expression." (PMID 34402718, 2021). "Similarly, kaempferol and quercetin have been shown to have a strong capacity to control tumorigenesis and progression via the regulation of tumor suppressor genes and molecular pathways, such as NF-κB, MAPK, and PI3K/Akt/mTOR." (PMID 33567572, 2021). "Here, through an in vivo genome-wide CRISPR screen in TNBCs, the authors identify tumorigenic functions for components of the mTORC1/2 complex and of the YAP/Hippo pathway, and demonstrate that pharmacological inhibition of mTOR and YAP reduces tumour growth in vivo." (PMID 34031411, 2021). "The tumor infiltration by immunocompetent cells and, consequently, the production of PD receptors and PD-L1, PD-L2 ligands by tumor cells are also controlled by an AKT/mTOR signaling cascade, transcription, and growth factors." (PMID 34681840, 2021). "Potential therapy resistance mechanisms involve the PI3K/AKT/mTOR signalling pathway, but tumour heterogeneity does not seem to play a role in resistance." (PMID 34256782, 2021). "Targeted agents have been investigated for GC treatment, such as: HER-2, EGFR, VEGF/VEGFR, PI3K/mTOR, PARP, MMPs inhibitors and agents that could induce tumor cell apoptosis." (PMID 34770912, 2021). "Consequently, a tumor’s biological behavior is mediated by a complex of molecular markers, which include the AKT/mTOR signaling pathway components, transcription and growth factors, and steroid hormone receptors and nuclear factors associated with them." (PMID 34319022, 2021). "Of the 7 without any mTOR treatment, 4 showed a spontaneous decrease in tumor size (2, 8, 9, and 13) at some points in time but growth at other time points." (PMID 33897589, 2021).
tumor (continued). "In elderly HGSOC, mutations in the genes that are involved in the Ras and or PIK3CA signaling pathways were detected in nine samples (15%), including the genes KRAS and BRAF (each one in 1 tumor); PIK3CB and MTOR (each one in 2 tumors); and NF1 (in three different samples)." (PMID 34944094, 2021). "Whereas optimum mTOR activity is pivotal for the function of NK cells, continuous hyperactivation of mTOR signaling, due to the persistent stress of the hypoxic TME, drives exhaustion and reduced anti-tumor capacity in NK cells." (PMID 34696286, 2021). "In addition to VHL, mTOR and PI3KCA genes were altered in tumor samples of clear cell renal cell carcinoma (ccRCC) patients." (PMID 33996789, 2021). "Further, quercetin inhibited tumor promotion by downregulating the pro-inflammatory cytokines IL-6 and IL-10; pro-survival molecules downstream of PI3K/AKT/mTOR, Wnt/β-catenin, and STAT3 such as c-FLIPL; and molecules linked to cell proliferation, including cyclin D1 and cMyc." (PMID 34950252, 2021). "Overall, up-regulating of SCRAR5 obviously inhibited CRC tumor growth in vitro and in vivo, which might be related to PI3K/AKT/mTOR pathway." (PMID 34417976, 2021). "Recent findings indicated that CXCR4 expression on tumor cells plays a positive role in key downstream pathways, including PI3K/AKT/mechanistic target of rapamycin kinase (PI3K/AKT/MTOR) and extracellular signal-regulated kinase 1/2 (ERK1/2), which promote tumor proliferation and migration." (PMID 34722241, 2021). "As for mTOR, its enhanced expression (≥2 scores) was not significantly correlated with any clinicopathological parameters such as tumor grade, stage, size, metastasis, survival rate, patients’ sex or age (P > 0.05), which was also observed in previous study." (PMID 34458019, 2021). "Three main tumor-related enriched pathways were detected in the LNM group, including mTOR signaling, Hippo signaling, and Wnt signaling pathways, while pathways related to leukocyte transendothelial migration or cytokine-cytokine receptor interaction were enriched in the non-LNM group." (PMID 34539886, 2021). "To explore the therapeutic properties of zotarolimus and mTOR drugs for CRC, we examined tumor growth and various aspects related to tumor development, including apoptosis, inflammation, and metastasis, with the objective of expanding the number of drugs available for CRC treatment." (PMID 34361836, 2021). "The metabolic landscape is also, in a large part, determined by the hypoxia-inducible factor 1-alpha (HIF-1α) in the hypoxic tumour environment, MYC, and other signalling pathways, including the phosphatidylinositol 3-kinase (PI3K)–AKT, NOTCH, and the mammalian target of rapamycin (mTOR)." (PMID 34968247, 2021). "The recognition of the PI3K/AKT/mTOR pathway as an important drug target in oncology led to the approval of PI3K inhibitors (as Idelalisib) and mTOR inhibitors (as an example of Sirolimus) for different neoplasias." (PMID 34638304, 2021). "Our study indicated that miR-124-3p played a tumor suppressor by directly interacting with PCDH8 and inhibiting the activation of the phosphatidylinositol 3-kinase (PI3K)/AKT/mammalian target of rapamycin (mTOR) signaling pathway." (PMID 34234863, 2021). "M1-3 had similar human tumour marker expression but diverse oncogenic signalling activation patterns, with OSAhigh M1 and M3 showing distinctive signalling: M1 had low p-Akt and p-NDRG1 and high p-p38 and M3 had high PI3K/mTOR effectors and high p-ERK." (PMID 33790302, 2021).